IL22 (interleukin 22)
Diseases named in the same sentence as IL22 in open-access papers (continued):
Sharing a sentence is not in itself a finding about the gene and the disease.
psoriasis (continued). "To investigate the role of IL-22, we first studied its expression regulation in psoriasis." (PMID 32632545, 2020). "Third, we could not evaluate the mechanisms by which AhR and autophagy regulate the adaptive immune system, for instance, by modulating the levels of cytokines critical in psoriasis pathogenesis, such as IL-17, IL-22, and IL-23 in the skin." (PMID 32235789, 2020). "IL-22 is highly expressed in psoriasis, but its expression is lower in AD." (PMID 32075269, 2020). "In future, we hope to address whether chrysin can reverse the inhibition of TNF-α, IL-17A, or IL-22-induced differentiation in keratinocytes in psoriasis." (PMID 32076123, 2020). "However, as psoriasis is an IL-17A dominated disease, we added IL-17A, IL-22, TNF-α and IFN-γ to our psoriasis-like HPKs." (PMID 32316273, 2020). "IL-17 and IL-22 induce IL-36 production in keratinocytes and blocking IL-36 attenuates the disease severity in a model of IL-23–induced psoriasis." (PMID 32345660, 2020). "IFN‐γ immunoreactivity decreased in psoriasiform reactions of patients 1 and 2, as compared to classical psoriasis, whereas IL‐22 positivity was significantly augmented in the infiltrate, in particular in cells with a macrophage‐like morphology (~2.1‐fold increase)." (PMID 31577850, 2020). "IL-17 and IL-22 are also important for chronic autoinflammatory diseases such as rheumatoid arthritis, inflammatory bowel diseases including Chron’s disease and ulcerative colitis, multiple sclerosis, and psoriasis." (PMID 32075269, 2020). "Of note, upregulation or dysregulation of IL-22 results in mostly detrimental effects in the skin, as aberrant control over its production results in hyperplasia of keratinocytes, resulting in conditions such as psoriasis and atopic dermatitis." (PMID 33003458, 2020). "We think that SA- and SD-administrated mice exhibited a positive reaction in the gut by increasing the activation of immune cells, such as Th17 cells, with the increased production of IL-17 and IL-22 aggravating as well the phenotype of psoriasis-like dermatitis." (PMID 32392785, 2020). "The expressed hIL22RA is thought to heterodimerize with endogenous IL10RB (IL10 receptor subunit beta), and this complex senses the presence of IL22, driving expression of output molecules to treat psoriasis, IL4 and IL10, via STAT3 (signal transducer and activator of transcription 3) signaling." (PMID 32185403, 2020). "NLP keratinocytes produce increased amounts of CCL20 upon stimulation with Candida albicans or mannan suggesting the role of KC, weakly stimulated by resident fungi, in accumulation of IL-17 and IL-22 producing CCR6-positive resident T cells in NLP skin of psoriasis patients." (PMID 32276410, 2020). "In addition, IL-22 aggravates psoriasis lesions in synergy with IL-17, although it exerts protective functions in non-psoriatic skin." (PMID 31295952, 2019). "We hypothesized that if a significant amount of IL-17A and IL-22 is produced by IL-17A/IL-22 dual secreting Th17 cells in psoriasis, then the gene expression of these two cytokines should correlate with one another." (PMID 31019502, 2019). "However, variable relationships amongst the expression of psoriasis susceptibility genes and of IL17A, IL22, and IL23A were identified." (PMID 31019502, 2019). "The IL-23/IL-17/IL-22 axis, which is induced by IL-36, plays an important role in psoriasis." (PMID 31736959, 2019). "Herein, we conduct meta-analyses of RNA-seq datasets to directly evaluate the current hypothesis that dual-secreting IL-17A/IL-22 Th17 cells are the dominant effector population in psoriasis." (PMID 31019502, 2019). "Similarly, in the imiquimod-induced psoriasis model that is IL-23/IL-17/IL-22–dependent, tofacitinib significantly reduced epidermal thickening and IL-17+ or IL-22+ lymphocyte infiltration into the dermis." (PMID 31649667, 2019).
psoriasis (continued). "Although dual-secreting T cells may exist, our results demonstrate that it is unlikely that the classical Th17 cells (IL-17A/ IL-22 dual-secreting T cells) play a universal role in psoriasis pathophysiology." (PMID 31019502, 2019). "Besides the local changes TNF, IFNγ, IL-2, IL-17, and IL-22 levels were found to be increased in serum of psoriasis patients." (PMID 31295952, 2019). "IL-22 is clearly a major cytokine involved in psoriasis pathophysiology." (PMID 31019502, 2019). "IL-22 is also a highly investigated cytokine involved in psoriasis pathophysiology." (PMID 31019502, 2019). "Other studies also have demonstrated that IL-22 is the most potent cytokine in this family in promoting hyperproliferation, cell differentiation, antimicrobial responses, and positive regulation of genes to promote tissue remodeling in psoriasis." (PMID 31311100, 2019). "Meanwhile, the mice exhibited higher serum levels of psoriasis mediators, such as interleukin-22 (IL-22), IL-17A and its downstream molecule regenerating islet-derived 3γ (Reg3γ), which has been confirmed to be a critical molecule in psoriatic epidermal hyperplasia." (PMID 31521168, 2019). "Thus, we sought evidence for the existence of dual secreting IL-17A/IL-22 Th17 cells within the psoriasis transcriptome." (PMID 31019502, 2019). "First line of the evidence connecting IL-22 to psoriasis pathogenesis comes from genetic studies." (PMID 30291393, 2019). "In imiquimod-induced psoriasis mice, IL-36Ra deficiency drove skin lesions and induced IL-23, IL-17, and IL-22 expression, whereas the wild-type mice did not develop skin lesions." (PMID 31736959, 2019). "Moreover, IL-6, IL-21, IL-22, IL-26, and IL-29, which participate to the amplification and maintenance of the inflammatory loop in psoriasis, all signal via STAT3." (PMID 29316631, 2018). "Furthermore, elevated IL-22 mRNA and protein levels in lesional skin and blood of psoriasis patients have been described." (PMID 29572462, 2018). "However, we found significantly increased IL22 expression in paradoxical psoriasis, which correlated significantly with the increased type I IFN expression (IFNA2r = 0.567, p < 0.005; IFNB1r = 0.474, p = 0.017; calculated by Spearman’s rank-correlation)." (PMID 29295985, 2018). "In psoriasis, pro-inflammatory cytokines including IL-17A, IL-22, TNF-α and IL-1α may contribute to the pathophysiology of the disease." (PMID 30180891, 2018). "Psoriasis is driven by T cell activation associated with the secretion of proinflammatory cytokines, including tumor necrosis factor-α (TNF-α), interleukin (IL)-17A, IL-22, and interferon IFN-γ." (PMID 30109481, 2018). "Likewise, in a model of psoriasis, Pla2g2d−/− mice display more severe epidermal hyperplasia than do Pla2g2d+/+ mice, with increased IL-17A+ or IL-22+ T cells in the affected skin and LNs." (PMID 30546811, 2018). "Indeed, the development of a IL-22-neutralizing antibody for the treatment of psoriasis, named fezakinumab, was discontinued and switched on atopic dermatitis." (PMID 29316717, 2018). "Since IL-22 does also play a harmful role as in the case of psoriasis, one might anticipate intervention of IL-22BP downregulation as a potential treatment option for psoriasis patients." (PMID 29572462, 2018). "It should therefore not be surprising that a cytokine which promotes proliferation of these cells could exacerbate the pathology or that an IL‐22 KO animal might be protective of psoriasis." (PMID 29713472, 2018). "The present meta-analysis found that TNF-α, IFN-γ, sE-selectin, IL-2, IL-6, IL-8, IL-18, IL-22, fibrinogen and C3 were elevated in serum of patients with psoriasis, indicating that serum levels of these cytokines may correlate to their levels in tissue." (PMID 29416693, 2018). "In addition, the positive correlation between IL-23/IL-17/IL-22 axis and psoriasis development has been demonstrated." (PMID 28623375, 2018).
psoriasis (continued). "These bioactivities suggest that IL-22 plays an important role in inflammatory skin processes and wound healing, but may be harmful to patients with psoriasis." (PMID 29679037, 2018). "Proinflammatory cytokines, in particular, IL-22 and IL-17, are also responsible for hyperproliferation and altered terminal differentiation of keratinocytes, as well as impairment of the apoptotic pathways, all typical features of psoriasis." (PMID 30581877, 2018). "Overall, IL-22 in human subjects seems to have weaker pro-inflammatory effects compared to the murine models, wherein IL-22 crucially contributes to the development of a psoriasis-like phenotype and to psoriatic skin inflammation induced by IL-23 or imiquimod." (PMID 29316717, 2018). "A recent clinical trial has demonstrated that oral delivery of Meriva (a lecithin based delivery system of curcumin) was effective as an adjuvant therapy for the treatment of psoriasis and was shown to significantly reduce serum levels of IL-22 and PASI scores in patients with mild-moderate disease." (PMID 29980703, 2018). "Elevated IL-22 levels have been detected in the blood plasma of patients with peripheral inflammatory diseases such as psoriasis and Crohn’s disease, and the severity of Guillain-Barré Syndrome (GBS) appears to correlate with CSF and plasma concentrations of this cytokine." (PMID 30542269, 2018). "Systemic IL-23 overexpression induced local inflammation in the enthesis by triggering resident IL-23R+RORγt+CD3+CD4−CD8− lymphocytes to secrete IL-17 and IL-22, ultimately leading to IL-17-dependent enthesitis, IL-22-dependent bone remodeling as well as aortic root inflammation and psoriasis." (PMID 29922283, 2018). "IL-23 induces and maintains the differentiation of IL-17- and IL-22-producing lymphocytes, which serve as the primary source of IL-17 and IL-22, both of which orchestrate epidermal hyperplasia and tissue inflammation in psoriasis." (PMID 29535706, 2018). "In addition, recent studies show that IL-22 production is increased in inflammatory diseases such as psoriasis and rheumatoid arthritis." (PMID 28558005, 2017). "Taken together, our study showed that CD147 is a novel and key mediator of IL-22-induced psoriatic alterations in the epidermis and might be a therapeutic target for psoriasis." (PMID 28272440, 2017). "Moreover, the ratio of IL-22/IL-22BP is positively correlated with psoriasis severity, implying the influence of IL-22 in pathogenetic immune circuits of psoriasis." (PMID 29232931, 2017). "The mouse model of psoriasis-like skin inflammation treated with IL-22-neutralizing antibodies could relieve inflammation, however treated with IL-22BP could aggravate disease in inflammatory bowel disease (IBD) model." (PMID 29182672, 2017). "3D skin equivalents made of GATA3 shRNA transduced cells showed the tendency to express less FLG when compared to the respective control 3D skin equivalent under all investigated conditions (ns, AD-like (IL-4 and IL-13), and psoriasis-like (IL-22, OSM, IL-17, and TNFα) conditions)." (PMID 28928464, 2017). "More recently, we showed in the imiquimod-induced psoriasis model in mice, known to be IL-22 dependent, that in vivo neutralisation of IL-22BP with the same neutralising antibody used in the present study led to increased severity of psoriasis-like skin inflammation." (PMID 28887540, 2017). "Together, these findings show that CD147 is a novel and key mediator of IL-22-induced psoriatic alterations in the epidermis and might be a therapeutic target in patients with psoriasis." (PMID 28272440, 2017). "However, research increasingly indicates that T-helper 17 (Th17) cells, which produce interleukin-17 (IL-17) and interleukin-22 (IL-22), are critical in the pathogenesis of psoriasis." (PMID 28761880, 2017).
psoriasis (continued). "Although extensive studies have not yet been performed, it is postulated that APECED patients may have a decreased incidence of psoriasis due to the presence of circulating anti-IL-17 and anti-IL-22 antibodies." (PMID 31548517, 2017). "Cytokines such as IL-1β, IL-17A, IL-22 and IL-23, which are involved in the pathogenesis of psoriasis, may also contribute to the production of IL-1β." (PMID 28266627, 2017). "Recent studies have shown that IL-22 is involved in many inflammatory diseases including psoriasis." (PMID 28272440, 2017). "After this stimulation, the downstream effector molecules of Th17 cells, including IL-17A, IL-22, TNF-α, and IL-6 are produced in response to certain stimuli and subsequently induce keratinocyte proliferation and other hallmark features of psoriasis." (PMID 28900461, 2017). "However, contrasting these reports IL-22 has frequently been identified as pro-inflammatory in a range of diseases including psoriasis, though little is understood about its role in PsA." (PMID 29163483, 2017). "Our findings indicate that the Lin− CD123low population may be an important and additional innate source of IL-22 and, importantly, IL-17 in the lesioned and probably in the NL skin of psoriasis patients." (PMID 28303135, 2017). "Several psoriasis-related cytokines, including IL-17a, IL-22 and IL-36γ, could up-regulate hS100A7 expression in keratinocytes." (PMID 28060905, 2017). "Moreover, treatment with TNF-α inhibitor can result in the reduced expression of IL-17 and IL-22 on the lesional psoriatic skin in patients with psoriasis." (PMID 29232931, 2017). "Effector cytokines, such as IL-17 and IL-22, produced by Th17 cells, induce hyper-proliferation of keratinocytes, production of proinflammatory cytokines, angiogenesis, and inflammation as part of the pathogenesis of psoriasis." (PMID 26901187, 2016). "So, IL-22 is suspected to be the main player in psoriasis pathogenesis." (PMID 28050571, 2016). "Unexpectedly, in GILZ-Tg mice, the severity of IMQ-induced psoriasis-like skin lesions as well as induction of cytokines commonly up-regulated in human psoriasis (Il-17, Il-22, Il-23, Il-6, S100a8/a9, and Stat3) was significantly more pronounced relative to GILZ-Wt mice." (PMID 27934944, 2016). "IL-22 is a member of IL-10 cytokine family that was discovered to be mainly produced by CD4+ T cells and associated with several autoimmune diseases such as inflammatory bowel diseases (IBD), psoriasis and systemic lupus erythematosus (SLE)." (PMID 27467597, 2016). "Thus, the data indicate that imiquimod-induced experimental psoriasis in mice shares many features of skin pathology and inflammatory pathogenesis of human psoriasis with increased IL-17 and IL-22 T cells." (PMID 26416167, 2015). "The biological role of IL-22 was initially described in hepatoma, pancreatic acinar cells and keratinocytes, thereafter reported to be involved in the pathogenesis of numerous inflammatory diseases, notably in skin inflammation such as psoriasis." (PMID 25793261, 2015). "In our experiments, the mRNA levels of IL-17, IL-22 and IL-23 were all overexpressed on day 14, and the protein levels of IL-17 and IL-23 also maintained high expression, which suggests this model can mimic the pathogenesis of psoriasis." (PMID 26691862, 2015). "Our work indicates that chemerin may be a regulatory target of IL-17 and IL-22 in epidermis, potentially influencing skin cell responses in psoriasis." (PMID 25659101, 2015). "IMQ is a ligand for Toll like receptors (TLR7 and TLR8) and when topically applied produces psoriasis-like skin lesions in mice which display many of the same characteristics as those observed in psoriasis in humans; elevations of IL-23/IL-17 and the dependency upon IL-22 to develop the lesions." (PMID 25965695, 2015).
psoriasis (continued). "Because IL-22 induces production of antimicrobial proteins in epithelial cells, the antibacterial activity of SLURP1 was assessed against Staphylococcus aureus (S. aureus), which is known to be associated with disease severity in psoriasis." (PMID 26474319, 2015). "Interestingly, we observed that only the treatment with topical methylprednisolone aceponate 0.1% plus Meriva was able to significantly downregulate the concentrations of IL-22 in the serum of patients with psoriasis." (PMID 26090395, 2015). "Thus, neoATB mice also exhibit more exacerbated skin disease in this IL-23-induced psoriasis model, which is again likely attributed to the increased IL-22-producing TCRγδ+Vγ4+ cells." (PMID 26416167, 2015). "In fact, IL-22 induces keratinocytes to produce antimicrobial peptides, S100 acute-phase proteins, and chemokines (such as IL-8) and chemokine receptors, thus leading to neutrophilic chemotaxis within psoriasis lesions." (PMID 26090395, 2015). "Our study also supports the notion that non-lesional skin of psoriasis patients is diseased skin, as some important psoriasis genes, such as IL-22, IL-19 and LCN2, were differentially expressed between thick and thin plaque psoriasis only within non-lesional skin." (PMID 26176783, 2015). "In psoriasis IL-17A, IL-17F, IL-22 and IL-20 act on keratinocytes leading to epidermal hyperplasia." (PMID 25153527, 2014). "Th1, Th17, and Th22 cells and IL-22 level were enhanced in psoriasis." (PMID 24899787, 2014). "Despite the high output of the IL-22 signaling pathway, miR-197 is down regulated in psoriasis." (PMID 25208211, 2014). "Th17 cells are an important source of inflammatory factors, including IL-17, IL-22 and IL-23, that may all have an effect on psoriasis, which leads to hyperkeratosis and parakeratosis." (PMID 24718773, 2014). "Moreover, neutralization of IL-22 prevented the development of psoriasis in a SCID mouse model of the disease." (PMID 25208211, 2014). "We hypothesized that cytosine methylation of the miR-197 putative promoter in psoriatic lesion compare to normal skin might be different and thereby explain why miR-197 is silenced in psoriasis despite the high levels of IL-22 in the patients’ blood." (PMID 25208211, 2014). "To verify whether the RHE genomic response to IL-17 stimulation was specific to IL-17, we stimulated RHE with IFN-γ or IL-22, cytokines thought to be involved in the psoriasis inflammatory cascade." (PMID 24587313, 2014). "In contrast, IL-22 regulates the development of the skin inflammation pathology seen in psoriasis." (PMID 24586644, 2014). "IL-22 plays a pivotal role in regulating host defense and inflammation and thereby upregulation of IL-22 production was seen in several human diseases like psoriasis, atopic dermatitis, and Crohn's disease." (PMID 24692846, 2014). "New cytokines and T cells populations, as IL-17A, IL-22, and Th22 cells, could play an important pathogenetic role in psoriasis and IBD." (PMID 23971052, 2013). "The importance of IL-22 has been highlighted in the pathogenesis of psoriasis." (PMID 23956763, 2013). "Furthermore IL-22 is able to induce a psoriasis-like phenotype in mice and blocking IL-22 by applying anti-IL-22 antibodies abates disease symptoms in this model." (PMID 23531535, 2013). "IL22 gene expression is elevated in inflammatory skin diseases like psoriasis or AD." (PMID 23531535, 2013). "In summary these date suggest a role for IL-22 in the pathogenesis of psoriasis." (PMID 23531535, 2013). "Methotrexate (MTX), an effective therapy for patients with psoriasis, was not able to cause significant reduction in the blood levels of IL-23, IL-17, IL-22, and Th17 cells in patients with rheumatoid arthritis." (PMID 24489536, 2013). "As with psoriasis, there is also increased IL-22 and IL-23 in the synovium of RA patients." (PMID 23956763, 2013). "Thus, IL-22 is considered to be an important inducer of keratinocyte proliferation in the pathogenesis of psoriasis." (PMID 22808266, 2012).